NQO1-DT (NQO1 divergent transcript)
Synonyms: FASRL
Gene: Long non-coding RNA gene on chromosome 16 (69,726,611 to 69,743,918, forward strand). Ensembl gene ENSG00000262136.
Diseases named in the same sentence as NQO1-DT in open-access papers:
NQO1-DT is named in the same sentence as 3 diseases in open-access papers, as found by Europe PMC text mining. Sharing a sentence is not in itself a finding about the gene and the disease.
NQO1-DT shares sentences with these, for which no sentence is quoted: hepatocellular carcinoma (6 papers); liver cancer (1); tumor (1).